FOXP3 (forkhead box P3)
Diseases named in the same sentence as FOXP3 in open-access papers (continued):
Sharing a sentence is not in itself a finding about the gene and the disease.
tumor (continued). "First, FoxP3+ T-cells are heterogeneous, involved in both regulatory and non-regulatory functions against tumor immunity." (PMID 32785290, 2020). "However, KO mice derived Treg cells exhibited remarkably reduced expression of Foxp3 and CTLA4 in both tumor tissue and dLNs, suggesting a compromised stability and function of Bcl6-dificient Treg cells." (PMID 32477338, 2020). "An analysis of tumor stroma was done using CD68 for macrophages, iNOS for type 1 macrophages (M1), CD206 and CD163 for type 2 macrophages (M2), CD3 for T-cells, CD8 for cytotoxic T-cells and FoxP3 for Treg." (PMID 32933105, 2020). "To explore the signaling pathway of tumor FOXP3, we found that FOXP3 could significantly downregulate oncogene c-Myc in HCC cells and our Reactome pathway analysis indicated that FOXP3 might act on the TGFβ/Smads pathway to exert its inhibitory function." (PMID 33116119, 2020). "The negative correlation between tumor stromal infiltration by FOXP3+ lymphocytes and SIR defined as elevated plasma CRP, as described in the present study, is congruent with that observation." (PMID 32316975, 2020). "As the most important component of the immune response in the tumor microenvironment of most solid tumors, tumor-infiltrating lymphocytes (TILs), represented by CD4+ Th, CD8+ CTLs, and CD4+/CD25+/FoxP3+ T reg, are only present in remarkably low numbers in the CNS compared to other tumor types." (PMID 33329549, 2020). "In addition, we found that when the endothelial cells overexpressing PD-L1 were injected into tumor tissues, the tumor immunosuppressive environment was further aggravated and the proportion of CD8/FoxP3 was declined." (PMID 32366856, 2020). "Finally, five model parameters were screened out in seven independent tumor-related immune features, including CD8, CD163, FOXP3, PD-L1, and Ki-67." (PMID 33154945, 2020). "Neuropilin-1 (NRP1) appears crucial to maintain intratumoural Treg stability without aberrant loss of Foxp3 identity, and anti-NRP1 displayed therapeutic efficacy in suppressing tumor growth." (PMID 32849557, 2020). "Although CD8+TIL density in the stroma area was strongly correlated with CD8+TIL density in the tumor area (r = .790, P < .001), Foxp3+TIL density in the stroma area was not correlated with Foxp3+TIL density in the tumor area (r = −.048, P = .502)." (PMID 32400056, 2020). "The percentage of CD44+CD62LlowT cells and Foxp3+T cells is comparable between in the dLNs of tumor-bearing mice treated by DMM or not." (PMID 32596169, 2020). "While a small increase in CD4+ FOXP3+ CD25+ Tregs was observed in the MC38 TNRs when compared to the control treated tumours this was not significant." (PMID 32705455, 2020). "Ablative radiation significantly increased infiltration of CD8+ cells expressing IFNγ (CD8+ effector T-cell) and CD4+ CD25+ FOXP3+ (Treg) cells to the tumor while hypofraction and conventional RT did not." (PMID 32287292, 2020). "Pharmacologically upregulating the STING pathway alone as an immunotherapy is unlikely to be successful as the recruited tumour specific T-cells can initiate immune inhibitory pathways including PD-L1 or FOXP3, thus preventing tumour clearance." (PMID 33081170, 2020). "Taken together, our findings indicate that the PD-L1 expression on VECs can realistically inhibit the immune-activation in microenvironment through promoting the aggregation of FoxP3+ T cells and inhibiting the function and infiltration of CD8+ T cells in tumor." (PMID 32366856, 2020). "Notably, small molecules inhibitors of PDGFRβ have been reported to augment tumor immunity by depletion of FoxP3-expressing Tregs and increase in CD8+ T cells in humans and advanced tumor-bearing mice." (PMID 32892748, 2020). "Mutant KRAS could up-regulate immunosuppressive cells in tumor such as myeloid-derived suppressor cells (MDSCs), CD4+FoxP3+ T regulatory cells, and CD19+IL10+ B regulatory cells." (PMID 32206449, 2020).
tumor (continued). "Th1 cells (CD3+ CD4+ T-bet+ Foxp3-) are also increased in the PBMC of HCC patients (2.41 ± 1.60), and even more increased in their peritumoral tissue (4.35 ± 1.49) and at the tumor site (12.97 ± 7.39); showing that the tumor microenvironment is an ongoing inflammatory response." (PMID 32182707, 2020). "We further observed patients with increased numbers of CD4+FOXP3+ T cells and CD8+ T cells in the tumor core have strong systemic immunity, which may be the mechanism of improved survival." (PMID 32377339, 2020). "Analysis of T cell composition within tumor samples in 102 patients with classical HL, where 29% of the tumor samples were positive for LMP1 by immunohistochemistry, demonstrated higher numbers of CD8+ T cells and CD4+/FoxP3+ T regs in samples from EBV-positive tumors." (PMID 33102204, 2020). "A fraction of CD8+ TILs can be bystanders and recognize non-tumor related viral antigens, whereas CD4+ TILs can be both bystander and/or forkhead Box P3 (FOXP3)+ tumor-specific T cells, which may be endowed with regulatory T cell functions." (PMID 33198174, 2020). "In FOXp3 stains, there was more widespread signal throughout the tumor mass, and not in surrounding tissue, suggesting a presence of regulatory T-cells." (PMID 32469935, 2020). "In practice, others have found that tumor hypoxia upregulates CCL28, a chemokine that recruits CD4+CD25+FOXP3+ Treg cells in an ovarian cancer mouse model, linking it to a more tolerigenic TME and increased tumor vascularization via vascular endothelial growth factor A." (PMID 35310881, 2020). "Tumor infiltration of CD8+ T cells was also significantly improved in all three treatment groups, along with a significantly increased CD8+/FoxP3+ Treg cell ratio." (PMID 33173046, 2020). "Tumors were harvested 20 days post tumor inoculation and analyzed by comparing the percentage of CD8+ and CD4+ cells in the CD45+ cell population, as well as the percentage of Treg+ cells in the CD45+/CD4+/foxP3+ cell population." (PMID 33218169, 2020). "Our immunofluorescence results confirmed that P60 was able to inhibit FOXP3 nuclear translocation in HCC cells, and the application of P60 could overcome FOXP3-mediated inhibition of tumor cell proliferation." (PMID 33116119, 2020). "CRC patients with node involvement exhibited a higher density of FoxP3-positive Tregs in the tumor stroma compared to those without node involvement." (PMID 32246094, 2020). "The localization of the CD4+Foxp3+ and CD4+LAG3+ T-cells remains instead more controversial, but it may be dictated by the expression of MHC-II on tumor cells." (PMID 33327433, 2020). "lnc-EGFR via regulating AP-1/NF-AT1/Foxp3 signaling pathway and lncRNA SNHG1 by regulating miR-448/IDO affect the differentiation and growth of immunosuppressive regulatory T cells (Tregs) and enable immune escape for tumor." (PMID 33281872, 2020). "Furthermore, we discovered the GC microenvironment with increased CD4+FOXP3+ T cells and CD8+ T cells (the High‐High group) had a robust IFN‐γ response and PDL1 expression, suggesting a strong immune activation in the tumor." (PMID 32377339, 2020). "Further exploration of the interaction between CD4+FOXP3+ T cells and CD8+ T cells may improve our understanding of tumor‐specific T‐cell activity in the tumor microenvironment, with potential impact on the development of immune‐modulatory therapies." (PMID 32377339, 2020). "Both CD4+ FOXP3+ and CD8+ FOXP3+ cells inhibit tumour rejection and promote tumour growth." (PMID 33276543, 2020). "CD3+ T cells (which include both CD4+ T cells and CD8+ T cells), CD8+ T cells, immunosuppressive CD3+FOXP3+ regulatory T cells (Tregs), and CD20+ B cells in the tumor nest and surrounding stroma were profiled and quantified by an automated quantitative pathology imaging system." (PMID 33352665, 2020).
tumor (continued). "For example, CD20+, CD4+ and FoxP3+ lymphocytes were all significantly higher in the stromal compartment of the ER/PR negative tumours (all p < 0.03), and all four subtypes were similarly more prevalent at the tumour edge." (PMID 32577938, 2020). "Furthermore, in the spleen and tumor tissues, the populations of CD8+ T cells and CD4+ Foxp3+ T cells were altered after DTSP vaccination." (PMID 32903495, 2020). "In this regard, as early as 5 days following 17D intratumoral treatment regimens, the absolute number of CD8 T cells per gram of tumor was increased, while CD4+FOXP3+ Tregs were markedly reduced in their numbers, resulting in high CD8/Treg and conventional CD4 T (Tconv)/Treg ratios." (PMID 31746149, 2020). "Significant differences in the density of FOXP3-positive TILs, CD204-positive tumor-infiltrating macrophages, PD-L1-positive cells, granulocyte-macrophage colony-stimulating factor (GM-CSF), and macrophage colony-stimulating factor (M-CSF) were observed in the quantitative analysis." (PMID 33121123, 2020). "Ablative RT combined with αPD-L1 mAb led to a significant increase in the number of CD8+ T cells expressing of IFNγ and Foxp3+ CD25+ expressing CD4+ T cells infiltrating into the tumor, but not into spleen or lymph nodes." (PMID 32287292, 2020). "We discovered that anlotinib could successfully promote CD8+ T cells to break through the “immune barrier” of VEC-PD-L1, infiltrate tumor tissues and significantly increase the ratio of CD8/FoxP3 compared with control group." (PMID 32366856, 2020). "Previously, we showed that Stat3 deletion in moDCs used as a tumor vaccine enhances accumulation of effector CD8+ and CD4+ T cells, and suppresses FoxP3+ CD4+ T cell (Treg) accrual in melanoma tumors, correlating with decreased tumor growth and increased mouse survival." (PMID 31947933, 2020). "Kaplan–Meier analysis revealed that CRC patients with high densities of ST2-positive cells and FoxP3-positive Tregs in the tumor stroma tended to have a significantly shorter overall survival time compared with patients with low densities of ST2-positive cells and FoxP3-positive Tregs." (PMID 32246094, 2020). "The relative proportions of CD8+, CD4+, CD4+FoxP3−, and CD4+FoxP3+ T cells in fresh tumour tissues were all independent of CRS (all p > 0.30)." (PMID 32418992, 2020). "In our current study, we uncovered that the pre-BCG tumor tissues of responders were presented with higher densities of CD8+PD-1+ as well as non-Treg CD4+FOXP3- T cells comparing with those of the non-responders." (PMID 33584702, 2020). "No FoxP3+ cells were detected in either tumor model, eliminating regulatory T cell-mediated immune suppression." (PMID 32121641, 2020). "The total bacterial load, as well as the number of FOXP3 positive cells in the tumor, according to our data, are not prognostic markers and do not affect the overall survival of patients." (PMID 32933105, 2020). "In this study, we demonstrated that the high expression of FOXP3 protein was correlated with less tumor number and early TNM stage, good overall survival and disease-free survival time, indicating that FOXP3 may act as a suppressor in HCC." (PMID 33116119, 2020). "Maternal exposure to HFD did not significantly change E0771 tumor infiltration of CD4+ T lymphocytes or T reg cells (CD4+FOXP3+ cells) in the offspring." (PMID 32580156, 2020). "In addition, CD8+ T cells, CD4+FOXP3+ T cells and DNT cells showed a significant difference in the immune cell: tumor cell ratio between the tumor core and edge." (PMID 32377339, 2020). "Given that CCL22 acted as an essential attractive signal of Tregs recruitment in various cancers, and that Foxp3 was the highly specific marker of Tregs, higher CCL22 and Foxp3 levels in HBV+ tumor implied higher intratumoral Tregs infiltration than HBV‐ tumors." (PMID 31769216, 2020).
tumor (continued). "We observed an increasing number of CD4+FOXP3+ T cells in the tumor do not correlate with a reduced MIN distance between CD4+FOXP3+ T cells and tumor cells (r = −0.01, P = 0.95)." (PMID 32377339, 2020). "The immune alteration mainly includes, but is not limited to, increased tumor infiltration of CD3+ and CD8+ T cells, reduction of immunosuppressive FoxP3+ regulatory T cells, and an increased ratio of CD8+ T cells/regulatory T cells (CD4+FoxP3+) (a hall mark of clinical efficacy)." (PMID 32050597, 2020). "High levels of stromal CD4+ and CD20+ cells associated with improved survival in hormone receptor negative cases (p < 0.04), while tumour nest CD8+ and FoxP3+ cells associated with poor survival in hormone receptor positives (p < 0.005)." (PMID 32577938, 2020). "Sixty tumor sections were stained with anti-CD8, anti-FoxP3, anti-PD-1, and anti-PD-L1 antibodies." (PMID 31138162, 2019). "MEG3 is defined as a tumor suppressor, but also regulates the balance of Treg cells and Th17 cells; downregulation of MEG3 increases forkhead box P3 (FOXP3) expression and inhibits retinoic acid receptor-related orphan receptor γt (RORγt) expression, to tip the balance in favor of Treg cells." (PMID 31547203, 2019). "In a single region of interest, among other cell types, tumor cells (Keratin+), T-helper cells (CD3+CD4+), cytotoxic T cells (CD3+CD8+), regulatory T cells (CD3+FOXP3+), HLA-DR+ macrophages (CD68+HLA-DR+), CD163+ macrophages (CD68+CD163+), and CD11c+ macrophages (CD68+CD11c+), were identified." (PMID 31736961, 2019). "A positive correlation was found between the numbers of tumor-infiltrating CD8–Foxp3+Tbet+ Tregs, CD8–Foxp3–Tbet+ (CD4) T cells and CD8 + Foxp3–Tbet+ T cells, supporting the notion that CD8–Foxp3+Tbet+ Tregs accumulate at similar sites as type 1-oriented (Foxp3-) effector T cells." (PMID 30658697, 2019). "We next investigated whether tumor growth delay in the unirradiated tumors was mediated by immune activation by analyzing the expression of CD8+/GzmB+ cells and CD4/Foxp3+ cells in TILs by flow cytometry." (PMID 30774761, 2019). "There were no remarkable differences of FoxP3 or RORγt mRNA levels between tumor and peritumor tissues (Student’s t tests, P = 0.303 and P = 0.954, respectively)." (PMID 30988066, 2019). "In GBM, in particular, some studies have shown a prognostic value of Foxp3+ tumour-infiltrating lymphocytes, and others not." (PMID 30830269, 2019). "Thus, a pretreatment tumor sample from the patient was analyzed for tumor-infiltrating CD8+ T cells, CD20+ B cells, and Tregs (FOXP3+ CD3+ T cells) by fluorescent mIHC." (PMID 30682845, 2019). "Furthermore, a positive relationship was found between the Foxp3 level and the CCL18 level in tumor tissues (R2 = 0.1098, p = 0.035)." (PMID 30216450, 2019). "There is accumulative evidence demonstrating that FoxP3+CD25+CD4+Treg cells prevent immune responses to cancerous cells and further demonstrating the Treg cells role in promoting tumour growth through inhibiting vaccine-stimulated antitumor immune reactions and preventing successful tumor control." (PMID 30693029, 2019). "Furthermore, ruxolitinib elevated numbers of tumor infiltrating CD4+IL17A+ Th17 and CD4+Foxp3+ regulatory T cells." (PMID 31407334, 2019). "However, in patients with tumours poorly infiltrated by CD66b, CD68 and FoxP3, CD20 infiltration did still appear to have a prognostic advantage." (PMID 31882709, 2019). "Baseline tumor biopsies from 196 patients in the NEOZOTAC trial were analyzed for CD8 (cytotoxic T-cells), FoxP3 (regulatory T-cells), CD68 (macrophages), and HLA class I (HCA2/HC10) expression by immunohistochemistry and subsequently related to pCR and disease-free survival (DFS)." (PMID 30868392, 2019). "Moreover, CD4+CD25+Foxp3+ Treg cells were quantified in tumors and showed significant increase in AAV-pCD4-shDNMT1-injected tumor but significant decrease in AAV-pCD4-DNMT1-injected tumor." (PMID 31006654, 2019).
tumor (continued). "A large tumor-regression area fulfilled the C-MTS with brisk lymphocyte infiltration, mainly composed of CD8+PD1+ T-cells, CD20+ B-cells, and scarce FOXP3+ cells." (PMID 31620131, 2019). "Although a subset of the activated CD4+ T cells expressed forkhead box protein P3 (FoxP3) and appeared to be T regulatory cells (Tregs), these cells did not significantly impact the anti-tumor vaccine response." (PMID 30956760, 2019). "Tregs were infiltrated into both tumor stroma and tumor cell nests, but the number of tumor-infiltrating Tregs was fewer than conventional T cells (FOXP3-negative CD3+ T cells) or CD8+ T cells." (PMID 30682845, 2019). "Compared with the controls (vehicle or no treatment), SLR14 treatment induced a significant increase of tumor-infiltrating CD45+ leukocytes, including CD11b+ myeloid cells, CD8+ T cells, and NK1.1+ cells, whereas CD4+ cells or CD4+FoxP3+ T reg cells were significantly decreased (top)." (PMID 31601678, 2019). "Therefore, we propose a strategy in order to convert CD8+FoxP3+ cells into ex-Foxp3+Tc17 cells and then into the Tc17/CTL population which plays a crucial role as final effector cells with cytotoxicity in the tumor microenvironment." (PMID 31024835, 2019). "Thus, patients exhibiting high CES2 expression show a distinct tumor immune profile with increased presence of CD8+ and FOXP3+ immune cells." (PMID 30867471, 2019). "We used multiplexed IHC and multispectral imaging to score five different tumour-infiltrating immune cells in CRC using well-established markers (CD8+ cytotoxic T lymphocytes, FOXP3+ T regulatory cells, CD20+ B lymphocytes, CD68+ macrophages, and CD66b+ neutrophils)." (PMID 31882709, 2019). "The increased levels of Foxp3+ and CD4+ cells along with enhanced mRNA expression levels of Foxp3 in the laparotomy group strongly indicate that laparotomy can result in an increase in Tregs population in tumor tissue." (PMID 30216450, 2019). "Interestingly, the frequency of Treg cells is correlated with the tumor load, and co-culture of CLL cells with CD4+ T cells induces a forkhead box P3+ (FoxP3+) Treg phenotype, indicating that CLL cells induce Treg differentiation." (PMID 31484424, 2019). "Furthermore, this intervention increases the fraction of intra-tumoral NK cells producing GzB and reduces the expression of PD-1, LAG3, FoxP3 and A2AR by tumor-infiltrating Tregs." (PMID 31244820, 2019). "Moreover, increased Foxp3+ and reduced CD3+ tumor-infiltrating lymphocytes correlated with IDO1 expression." (PMID 31412566, 2019). "To explore the immune response against tumors in CRC model mice, we performed immunohistochemical analysis (IHC) to analyze the Foxp3, CD8, and Granzyme B expression after therapy; this was quantified as the number of positive cells divided by total cells in the tumor microenvironment." (PMID 31882868, 2019). "It was reported that, FOXP3 expression in some hepatoma cell lines and HCC sections revealed that 48% of HCC displayed FOXP3 staining, but FOXP3 staining were absent in normal liver tissues and para-tumor tissues." (PMID 31653148, 2019). "An indication of the presence of primarily FoxP3+ non-Tregs in a tumour is increased expression of IL-12 and TGF-β." (PMID 30232514, 2019). "The main mechanisms that eliminate tumor cells in CRC are gamma IFN and TNF (α and β) producing CD4 + TH1 cells and IL10 secreted by FoxP3+ regulatory T cells by NK or γδ T cells that suppress or downregulate induction and proliferation of effector T cells at the tumor site." (PMID 31303863, 2019). "In addition, lymphocytes play important roles in tumour immunity; for example, CD8+ cytotoxic T-cells damage tumour cells, whereas CD4+Foxp3+ regulatory T-cells suppress the function of these cells." (PMID 31462002, 2019). "Besides, CD19+CD25hi Bregs inhibit the proliferation of CD4+ T cells by secreting IL-10 and TGF-β and promote the expression of FoxP3 and CTLA-4 in the Tregs, both of which are Tregs tumor suppressor markers." (PMID 31662750, 2019).